ZSCAN5B (zinc finger and SCAN domain containing 5B)
Description:
May be involved in transcriptional regulation.
Synonyms: ZNF495B; ZNF371
Tractability: PROTAC: ubiquitination databases record sites on it.
Gene: Protein-coding gene on chromosome 19 (56,189,686 to 56,197,815, reverse strand). Ensembl gene ENSG00000197213.
Subcellular location: Nucleus
Subcellular location (Human Protein Atlas): Nuclear speckles
Gene Ontology:
Molecular function: protein binding; DNA-binding transcription factor activity, RNA polymerase II-specific; RNA polymerase II cis-regulatory region sequence-specific DNA binding
Biological process: regulation of transcription by RNA polymerase II
Cellular component: nucleus
Genetic constraint (gnomAD): Loss-of-function variants: 26 observed, 24.17 expected, observed/expected ratio (o/e) 1.08, 90% interval 0.79 to 1.49. The upper end of that interval is the gene's LOEUF score, 1.49, which puts it in group 6 of 6, group 1 being the genes least tolerant of losing a copy. Missense variants: 745 observed, 629.63 expected, observed/expected ratio (o/e) 1.18, 90% interval 1.11 to 1.26. Synonymous variants: 244 observed, 246.04 expected, observed/expected ratio (o/e) 0.99, 90% interval 0.89 to 1.1.
Homologues: Orthologues: chimpanzee ZSCAN5B (95% identical), rat Zscan5b (41% identical), mouse Zscan5b (41% identical), Drosophila melanogaster CG12391 (14% identical), zebrafish plagl2 (11% identical), Drosophila melanogaster hb (11% identical), zebrafish ovol1a (11% identical), zebrafish ovol1b (9% identical), zebrafish plagx (9% identical), Caenorhabditis elegans hbl-1 (8% identical), Caenorhabditis elegans lin-48 (8% identical), Caenorhabditis elegans Y5F2A.4 (7% identical). Paralogues in human: ZSCAN5A (79% identical), ZSCAN5C (76% identical), ZSCAN29 (25% identical), ZKSCAN2 (25% identical), ZNF18 (25% identical), ZSCAN32 (24% identical), ZNF174 (23% identical), ZNF202 (23% identical), ZNF496 (23% identical), ZNF274 (22% identical), ZNF446 (18% identical), ZNF444 (17% identical), and 17 more.